TMEM92 (transmembrane protein 92)
Synonyms: FLJ33318
Tractability: Antibody: UniProt predicts a signal peptide or a membrane-spanning region.
Gene: Protein-coding gene on chromosome 17 (50,271,406 to 50,281,485, forward strand). Ensembl gene ENSG00000167105.
Subcellular location: Membrane
Subcellular location (Human Protein Atlas): Nucleoplasm
Gene Ontology:
Molecular function: protein binding
Cellular component: membrane
Genetic constraint (gnomAD): Loss-of-function variants: 16 observed, 15.98 expected, observed/expected ratio (o/e) 1, 90% interval 0.68 to 1.52. The upper end of that interval is the gene's LOEUF score, 1.52, which puts it in group 6 of 6, group 1 being the genes least tolerant of losing a copy. Missense variants: 174 observed, 210.78 expected, observed/expected ratio (o/e) 0.83, 90% interval 0.73 to 0.94. Synonymous variants: 85 observed, 87.65 expected, observed/expected ratio (o/e) 0.97, 90% interval 0.81 to 1.16.
Homologues: Orthologues: chimpanzee TMEM92 (98% identical), macaque TMEM92 (92% identical), rabbit TMEM92 (67% identical), pig TMEM92 (65% identical), dog TMEM92 (55% identical), rat LOC100364194 (44% identical), mouse Tmem92 (41% identical), rat LOC103693451 (40% identical).
Diseases named in the same sentence as TMEM92 in open-access papers:
TMEM92 is named in the same sentence as 7 diseases in open-access papers, as found by Europe PMC text mining. Sharing a sentence is not in itself a finding about the gene and the disease. The quoted sentences say what the papers report.
pancreatic cancer (3 papers, 2023 to 2025). "For example, TMEM92 is a pivotal biomarker of immune resistance in pancreatic cancer, and its elevated expression is associated with poor prognosis and suboptimal immunotherapy outcomes." (PMID 41425710, 2025). "Based on the expression characteristics of these genes, we found that the TMEM92 gene was highly expressed in malignant epithelial cells of pancreatic cancer and was significantly associated with an immunosuppressive tumor microenvironment." (PMID 37265785, 2023). "Transmembrane protein 92 (TMEM92) mRNA expression has been identified as an immune resistance and prognostic marker in pancreatic cancer." (PMID 39941003, 2025). "To further investigate the clinical significance of TMEM92 in pancreatic cancer, we performed immunohistochemical analysis and found that patients with high TMEM92 expression had poor prognosis." (PMID 37265785, 2023). "Significant upregulation of TMEM92 was observed in 25 cases of pancreatic cancer tissue, and survival analysis revealed a strong correlation between elevated TMEM92 expression and poor prognosis." (PMID 37265785, 2023). "Moreover, through bulk RNA-sequence and immunohistochemical staining we verified the protein expression of TMEM genes in PDAC and revealed TMEM92 as an essential regulator of pancreatic cancer cell proliferation, migration, and invasion." (PMID 37265785, 2023).
breast carcinoma (1 paper, 2023). "For example, TMEM92 was reported to act as an oncogene to support malignant cells growth, invasiveness and motility through regulating the EMT relative proteins in breast cancer." (PMID 37564657, 2023).
head and neck squamous cell carcinoma (1 paper, 2026). A squamous cell carcinoma that arises from any of the following anatomic sites: lip and oral cavity, nasal cavity, paranasal sinuses, pharynx, larynx, and salivary glands. "Transmembrane protein 92 (TMEM92) has been implicated in tumor progression in several malignancies, yet its role in head and neck squamous cell carcinoma (HNSCC) remains unclear." (PMID 42045453, 2026).
lymph node metastasis (1 paper, 2026). "Moreover, elevated TMEM92 expression was associated with lymph node metastasis, an immunosuppressive tumor microenvironment, and a poor predicted response to immunotherapy." (PMID 42045453, 2026).
tumor (4 papers, 2023 to 2026). "Re-expression of DDX3X rescued the anti-tumor effects induced by TMEM92 knockdown." (PMID 42138474, 2026). "In the case analyses, genes such as TMEM92 and C1orf226 showed consistent expression in pretreatment surgically resected tumor tissues, and posttreatment blood may be indicators of GBM." (PMID 36697401, 2023).
TMEM92 also shares sentences with these, for which no sentence is quoted: malignant tumor (1 paper); triple-negative breast carcinoma (1).